RXRA (retinoid X receptor alpha)
Diseases named in the same sentence as RXRA in open-access papers (continued):
Sharing a sentence is not in itself a finding about the gene and the disease.
bladder cancer (19 papers, 2016 to 2023). "Accordingly, in a different subtype of bladder cancer, muscle-invasive bladder cancer, recurrent mutations in RXRα lead to an imbalance of the PPARγ/RXRα heterodimer, and focal amplification of PPARγ." (PMID 35954274, 2022). "Recent whole-exome sequencing studies have identified the RXRα S427F hotspot mutation in 5% of the bladder cancer patients, which is always located at the interface of RXRα with its obligatory dimerization partners." (PMID 34820085, 2021). "In the literature some evidence is present in relation to RXRα and PPARγ genes mutations in bladder cancer that can cause PPARs/RXRα pathway hyperactivation resulting in the cellular proliferation, even though they were not related to ATRA treatments." (PMID 32756427, 2020). "It has recently been suggested that activation of the PPARγ/RXRα pathway via mutations in PPARG or RXRA promotes tumorigenesis in luminal bladder cancer." (PMID 33266062, 2020). "Here, we report recurrent mutations of PPARγ that also activate the PPARγ/RXRα pathway, conferring PPARγ-dependency and supporting a crucial role of PPARγ in luminal bladder cancer." (PMID 30651555, 2019). "Activation of the PPARγ/RXRα pathway in luminal bladder cancers has mainly been linked to PPARG gene amplifications and activating point mutations in RXRα." (PMID 30651555, 2019). "Although outside the scope of this study, the role of this RXRA mutation in bladder cancer should be characterized in detail as another potential therapeutic avenue for patients with advanced bladder cancer." (PMID 30176882, 2018). "Between 5–8% of people with bladder cancer have a mutation in the gene that produces a protein called RXRA." (PMID 29143738, 2017). "Exome analysis of bladder cancer samples across three independent cohorts identified mutations at RXRA S427 in 5–8% of cases, always leading to an amino acid substitution with an aromatic amino acid, phenylalanine (~5%) or tyrosine (~1%)." (PMID 29143738, 2017). "Here, we report that hotspot S427F/Y mutations in RXRA or focal amplification/overexpression of PPARG in bladder cancer induce the activation of the PPARγ/RXRα pathway, leading to suppression of cytokine secretion from cancer cells." (PMID 28740126, 2017). "This network module contains the known bladder cancer driver TSC1 (and 9 other-known cancer drivers) and 5 putative bladder cancer drivers one of which is RXRA, whose mutation activates the peroxisome proliferator-activated receptors, which switch on genes driving cell proliferation." (PMID 35035776, 2022). "RXRα hotspot mutations appear to be specific to bladder cancer." (PMID 30651555, 2019). "Contrarily, it has been reported that the activation of PPARγ/RXRα induces the microenvironmental reprogramming in the bladder cancer, which is beneficial to the tumorigenesis." (PMID 37976136, 2023). "The abnormal expression of RXRα was reported in a variety of cancers such as bladder cancer, renal cancer and oesophageal cancer." (PMID 33128348, 2020). "Our study provides additional genetic evidence for a pro-tumorigenic role of PPARγ in bladder cancer and strengthens the importance of the PPARγ/RXRα pathway in luminal bladder cancer." (PMID 30651555, 2019). "Here, we characterize mutant RXRA, demonstrating it induces enhancer/promoter activity in the context of RXRA/PPAR heterodimers in human bladder cancer cells." (PMID 29143738, 2017). "TCGA data were first queried to determine which of the three PPARs are most highly expressed in bladder cancer specimens with mutant RXRA." (PMID 29143738, 2017).
bladder cancer (continued). "Collectively, these data reinforce the anti-inflammatory role of tumor-intrinsic PPARγ/RXRα activity and potentially as a driver of resistance to immune checkpoint inhibitor therapies in bladder cancer." (PMID 28740126, 2017). "We demonstrate that recurrent alterations in PPARγ/RXRα heterodimer lead to enhanced PPARγ signaling, reinforcing the importance of this pathway in bladder cancer biology." (PMID 28740126, 2017). "To establish a causal role of RXRA hot-spot mutations in hyper-activation of PPAR singling, we used retroviral transduction to introduce wild-type or mutant RXRA into two bladder cancer cell lines, JMSU-1 and 575A." (PMID 29143738, 2017). "FDA approved drugs such as tretinoin and bexarotene have been shown to modulate RXRA expression level and therefore could potentially be repurposed for the treatment of bladder cancer." (PMID 35035776, 2022). "Interestingly, PPARγ Q286E found in bladder cancer induces a constitutively active conformation of PPARγ LBD and thus abnormal activation of PPARγ/RXRα pathway, which suggests tumorigenic roles of PPARγ in bladder cancer." (PMID 33266062, 2020). "Furthermore, chemokines CCL2 and CXCL10, which contribute to immunosurveillance, were induced by shRNAs of PPARγ and RXRα in HT-1197 bladder cancer cells bearing endogenous RXRαS427F." (PMID 28740126, 2017). "Importantly, human bladder cancer samples appear to express both PPARD and PPARG and our data suggest both are activated by mutant RXRA and play a role in transcriptional hyperactivity in human bladder cancer cells." (PMID 29143738, 2017). "Thus, both PPARD and PPARG contribute to mutant RXRA-mediated transcriptional hyperactivity in human bladder cancer cells and appear to have redundant function." (PMID 29143738, 2017). "We also explored the possibility that RXRA or PPARG alterations may be restricted to subtypes of bladder cancer classified by expression and genomic profiles." (PMID 28740126, 2017). "Collectively, we posit that this resistance phenotype may be reversed by therapeutic targeting of PPARγ/RXRα offering a therapeutic approach to sensitizing bladder cancer with activated PPARγ/RXRα pathway to immunotherapies." (PMID 28740126, 2017). "Therefore, RXRαMUT preferentially and constitutively interact with PPARγ to activate PPARγ/RXRα-mediated signaling activity in the bladder cancer cells." (PMID 28740126, 2017). "However, the PPARγ Q286E mutation found in bladder cancer increased PPARγ transactivation by inducing the active conformation, favoring the recruitment of RXRα and co-activators without ligand binding." (PMID 33266062, 2020). "Although we cannot completely exclude the potential role of PPARγ/RXRα in transformed cell autonomous phenotypes, our data suggest that induction of microenvironmental reprogramming favored by tumorigenesis is a key function of PPARγ/RXRα activation in bladder cancer." (PMID 28740126, 2017). "Such therapies could also benefit the approximately 15–20% of people with bladder cancer who do not have the RXRA mutation but who do have over-active PPARs." (PMID 29143738, 2017). "3.30.50.10.FF4220, a nuclear receptor family particularly likely to be free of side effects, contains proteins such as RXRA, RXRB and RXRG which show high expression in bladder cancer and are currently drug targets in other cancers (breast and prostate)." (PMID 35035776, 2022). "Mutant RXRA-driven growth of urothelium is reversible by PPAR inhibition, supporting PPARs as targetable drivers of bladder cancer." (PMID 29143738, 2017). "The vast majority of PPARγ/RXRα active tumors were presented in Cluster I, a subset of luminal bladder cancer, suggesting PPARγ/RXRα activation may contribute to lack of response to immunotherapy." (PMID 28740126, 2017).
bladder cancer (continued). "However, it was not clear what mutant RXRA proteins do in bladder cancer cells." (PMID 29143738, 2017). "Since hyperactivity of mutant RXRA was dependent on PPAR expression, we reasoned that no hyperactivity would be observed in the DR-1 luciferase reporter assay in a bladder cancer cell line with low endogenous expression of PPARs." (PMID 29143738, 2017).
diabetes (15 papers, 2011 to 2024). "Pathways linked to immunometabolism were of particular interest, including type 1 and type 2 diabetes mellitus signaling, PPARα/RXRα activation, cyclic AMP (cAMP)-mediated signaling, and HIF1α signaling." (PMID 31825836, 2019). "The nuclear receptors peroxisome proliferator-activated receptor γ (PPARγ) and its hetero-dimerization partner retinoid X receptor α (RXRα) are considered as drug targets in the treatment of diseases like the metabolic syndrome and diabetes mellitus type 2." (PMID 29057944, 2017). "Using an in vivo type 2 diabetic animal model, we provided additional evidence supporting a role of RARα and RXRα in the diabetes-induced development of cardiac remodeling." (PMID 26237391, 2014). "It plays key roles in various biological processes including cancer, diabetes, obesity, and atherosclerosis, and both agonist and antagonist of RXRα have been revealed to exert beneficial effects in such diseases." (PMID 21792151, 2011). "These metabolites might show beneficial effects against intractable diseases with relation to RXRα, for example anti-cancer and anti-diabetes." (PMID 21792151, 2011). "Treatment with GYY substantially mitigated the elevated expression of RXRα, RXRβ and RARγ1, suggesting an RXR and RAR regulatory role by GYY to mitigate PAI-1, MMP-9, MMP-13; thus, ECM turnover in diabetic kidney." (PMID 34680110, 2021). "Based on these data, it is likely that diabetes-induced oxidative stress and activation of JNK promotes degradation and transcriptional inhibition of RARα and RXRα, through phosphorylation of RARα and RXRα at specific phosphorylation sites." (PMID 26237391, 2014).
lung carcinoma (15 papers, 2010 to 2025). "For RXRA, from a group of vitamin D-related genes, associations were reported for leukemia, breast and lung cancer." (PMID 33647036, 2021). "RXRA is known to inhibit non-small cell lung cancer cell growth and is a therapeutic target for lung cancer." (PMID 39172974, 2024). "Real time qPCR revealed that RXRα siRNA#3 markedly inhibited KRT7-AS expression in lung cancer A549 cells." (PMID 37185462, 2023). "A recent study indicates that RXRA is involved in cell cycle regulation and lung cancer development, in this case, it is regarded as the potential target gene of lung cancer." (PMID 33506873, 2021). "EGCG can also prevent lung cancer relapse in lung cancer mouse xenografts by blocking the cancer stem-cells-like growth through the modulation of the hsa-mir-485-5p/RXRα axis and downregulating protein acetylation in lung carcinoma cells." (PMID 31744117, 2019). "Accordingly, we speculated that the mechanisms of ADI on treating lung cancer were associated with the regulation of ESR1, NCOA1, RXRA, and RELA." (PMID 33506873, 2021). "Initially, using the lung cancer dataset, it was identified in VEGFC and proteins from the treatment datasets: RXRA, PPARG, and SMO." (PMID 40334012, 2025). "Because tumor samples had lower RXRα expression, we interrogated whether the expression of RXR could predict survival in breast and lung cancer patients." (PMID 34638488, 2021). "As SR11302 is a known compound with strong anti-AP-1 activity with selective binding with RARα and RARΥ, but not with RARβ and RXRα, it provides important evidence that the AP-1 complex may play an important role in CTC survival and, ultimately, tumor metastasis in lung cancer." (PMID 29177791, 2017).
prostate carcinoma (15 papers, 2004 to 2025). A carcinoma that arises from epithelial cells of the prostate gland. "It was showed that reduced RXRα tended to a higher risk of distant failure after radiotherapy in prostate cancer." (PMID 33128348, 2020). "Inactivation of RXRα in the prostate epithelium led to the development of preneoplastic lesions in mice, while RXRα overexpression caused cell growth reduction or increased susceptibility to apoptosis in prostate cancer cells." (PMID 31212954, 2019). "RXRα, an important transcription factor, was also shown to be involved in the progression of various tumors, such us acute myeloid leukemia and prostate cancer." (PMID 41276823, 2025). "Compared to normal tissues, the content of RXRA in prostate cancer is relatively low, and this low expression is negatively correlated with relapse-free survival and an increased risk of distant recurrence following radiotherapy." (PMID 40781327, 2025). "MiR-191 promotes resistance of prostate cancer to radiation by targeting retinoid X receptor alpha (RXRA)." (PMID 36732504, 2023). "miR-191 modulates radiation resistance of prostate cancer through interaction with Retinoid X receptor alpha, RXRA." (PMID 33505907, 2020). "Using retinoids to improve RXRα expression can enhance the sensitivity of prostate cancer to radiotherapy, although the other two isoforms of RXR, β and γ, also have some anti‐tumour effects." (PMID 33128348, 2020). "In contrast, the expression levels of several NRs including LXRα, LXRβ, RARγ, and RXRα are downregulated in malignant-transformed prostate epithelial RWPE-2 cells as well as clinical prostate cancer samples." (PMID 31212954, 2019). "Although AT treatment did not affect the mRNA levels of the androgen-responsive genes assessed, AT produced a 20% reduction in RXRα mRNA levels, providing further support for differential effects of AT and TQ on prostate cancer cells." (PMID 26986969, 2016). "However, the overexpression of RXRα results in the proliferation of prostate cancer cells decreasing and inducing apoptosis." (PMID 39771106, 2024). "In addition, they demonstrated that miR-191 promoted radioresistance in prostate cancer cell lines and suggested this occurred through the ability of miR-191 to target retinoid X receptor alpha (RXRA)." (PMID 36233505, 2022). "MiR-191 could promote tumorigenicity in breast via interacting with estrogen and radiation survival in prostate cancer by interacting with Retinoid X receptor (RXRA)." (PMID 34252883, 2021). "Previous studies confirmed that EPHX2, RXRA, LTC4S and SLC25A17 were abnormally expressed in prostate cancer tissues and affected the malignant biological behaviour of prostate cancer cells and prognosis of patients." (PMID 36643625, 2023). "In previous studies, it has been shown that the expression level of RXRα in prostate cancer is diminished compared to in non-malignant prostate tissue." (PMID 39771106, 2024). "Previous studies showed that the expression of RXRα was reduced in prostate cancer compared with nonmalignant prostate." (PMID 31212954, 2019).
colorectal cancer (13 papers, 2013 to 2025). A primary or metastatic malignant neoplasm that affects the colon or rectum. "Indeed, it was found that the repression of RXRα phosphorylation, a malfunction associated with colorectal cancer, restored the RXRα-PPARγ heterodimer formation and led to the PPARs target genes induction and AP-1 activity suppression." (PMID 32012980, 2020). "The RXRα expression was examined using Western blot and was found to be different in four colorectal cancer cell lines." (PMID 33128348, 2020). "As a result of the abnormal expression of RXRα in various cancers, the differences in RXRα expression were determined between 20 pairs of colorectal cancer tissue and para‐carcinoma tissue." (PMID 33128348, 2020). "Our earlier report that RXRα expression is silenced in the AOM/Apc Min/+ mouse model for colorectal cancer prompted an exploratory analysis of RXRα protein expression in human colorectal cancers and established colorectal cancer cell lines." (PMID 27167203, 2016). "To assess RXRa expression in human colorectal cancers we used a commercial tissue microarray and stained for RXRα and β-catenin expression in the microdissected tissue samples including colorectal cancers, tissue adjacent to and distant normal tissue." (PMID 27167203, 2016). "Hence, RMST suppresses colorectal cancer progression by regulating the miR-27a-3p/RXRα axis and blocking Wnt signaling." (PMID 40871106, 2025). "Polymorphisms in the calcium sensing receptor gene and RXRA have been associated with colorectal cancer risk, but to our knowledge no previous studies have evaluated these genes in relation to pancreas cancer risk." (PMID 23826131, 2013). "While we demonstrated downregulation of RXRα expression in the colorectal cancer samples in the array, we did not have access to pertinent clinical information to correlate tumor phenotype with impaired RXRα expression and possible associations with CIMP+ status." (PMID 27167203, 2016). "Functional heterogeneity exists among subtypes: FABP7 drives glioblastoma stem cell migration via RXRα signaling, while FABP5 exhibits context-dependent roles, promoting HCC progression but suppressing colorectal cancer (CRC) through mTOR-mediated autophagy." (PMID 40717587, 2025). "However, the anti‐metastatic effect of 20(S)‐PPD and the effect of 20(S)‐PPD on RXRα and EMT level in colorectal cancer cells are largely unknown." (PMID 33128348, 2020).
type 2 diabetes (11 papers, 2007 to 2024). "PPARγ is a target for pharmaceutical intervention in type 2 diabetes, and insight into interactions between PPARγ, RXRα, and DNA is of interest in understanding the function and regulation of this complex." (PMID 25954810, 2015). "RXRA is a member of the Retinoid × Receptor family which is reported to play an important role in different metabolic disorders including type 2 diabetes." (PMID 19575795, 2009). "In this review, we address hepatokines identified in the pathogenesis of NAFLD and NASH, including the signaling of FXR/RXR, PPARα/RXRα, adipogenesis, hepatic stellate cell activation/liver fibrosis, AMPK/NF-κB, and type 2 diabetes." (PMID 36267567, 2022).
atherosclerosis (10 papers, 2009 to 2025). A disease characterized by the build-up of fatty material and calcium deposition in the arterial wall resulting in partial or complete occlusion of the arterial lumen. "Out of 249 genes in significant modules that were not enriched in pathways or networks, four genes, LMNA and MMP12 at baseline, NPY and RXRA in females and males at 2y have previously been shown to be associated with atherosclerosis." (PMID 35925965, 2022). "For example, the transcription of Per2 is regulated by RXRα, the ligand of PPARα, which regulates lipid and lipoprotein metabolism, and inflammation, major risk factors for atherosclerosis." (PMID 20040117, 2009). "RXRA promotes cholesterol efflux from macrophages, which is beneficial for preventing atherosclerosis." (PMID 40723896, 2025). "Bexarotene, one of the small molecules predicted for target RXRA gene, can improve cholesterol homeostasis and inhibit atherosclerosis progression in a mouse model of mixed dyslipidemia." (PMID 36923793, 2023). "From our score regressions, the atherosclerosis signaling pathway, IL-12 signaling and production in macrophages, PPARa/RXRa activation, MODY signaling, and complement system had the strongest associations with AUCs being 1.36-1.45 times the AUC of the clinical baseline model." (PMID 37308820, 2023). "Three transcriptional regulators such as RXRA, SOX7, and FOXA2, that have been predicted to bind with SNP rs3136441 in the presence of allele C, may have the pathogenetic role for atherosclerosis." (PMID 35203469, 2022).